PECAM1 (platelet and endothelial cell adhesion molecule 1)
Diseases named in the same sentence as PECAM1 in open-access papers (continued):
Sharing a sentence is not in itself a finding about the gene and the disease.
tumor (continued). "highlights six genes (VEGFA, KDR, ESM1, CD34, PECAM1, and ANGPTL4), but only four of them were expressed by endothelial cells while VEGFA and ANGPTL4 were mainly expressed by tumor cells." (PMID 36423636, 2022). "Compared to controls, tumor displaying lower SNAI1, PECAM1 and VIM and higher TP63, KRT14, KRT5 and PTPRC (CD45) RNAs (PyMT-VE-CadhSnail1KO tumor signature) presented a longer overall survival, strengthen our mice results." (PMID 34335957, 2021). "The number of endothelial cells in the tumour sections per high power microscope field (approximately 0.04 mm2), was also determined by staining with an anti-PECAM-1 antibody (anti-PECAM-1-Alexa-488)." (PMID 33670520, 2021). "Based on the Tumor Immune Estimation Resource (TIMER) database, the relationship between PECAM1 expression and B cell, CD8+ T cell, CD4+ T cell, macrophage, neutrophil, and dendritic cell infiltration was weak in LUAD (P<0.01)." (PMID 33461176, 2021). "Circulating tumor endothelial cells (CTECs) refer to the platelet endothelial cell adhesion molecule-1 (PECAM-1, CD31)+ tumor endothelial cells (TECs) shedding into peripheral blood." (PMID 34680256, 2021). "In 88 paired samples, LRRK2, PECAM1, EPAS1, and LDB2 showed significant low expression in tumor samples, which was consistent with previous results." (PMID 32196072, 2020). "CD31 (platelet endothelial cell adhesion molecule-1, PECAM-1) is expressed in blood vessels and lymphatic endothelial cells and involved in tumor angiogenesis and metastasis." (PMID 32318337, 2020). "Additionally, in our further study, it will be interesting to determine the individual roles of MMP-9, PDGFR-α, and PECAM-1 during lung metastasis as well as to learn whether the functions of MMP-9, PDGFR-α, or PECAM-1 are tumor-type or cancer cell-type specific." (PMID 30483898, 2019). "At the end of 4 weeks, animals were euthanized and tumours were excised and probed using markers of proliferation (Ki67), micro-vessel density (MVD) (CD31/PECAM1) and cell death (necrosis via H&E staining)." (PMID 30046049, 2018). "IHC staining of the endothelial marker CD31 (also known as PECAM1) revealed differences in both the mean vessel density and the average vessel diameter between tumor locations." (PMID 29903803, 2018). "Both PECAM1 and ADCY7 promoted tumor progression through the AKT pathway, showing the same molecular mechanism as CD300A." (PMID 29938007, 2018). "In contrast, in tumor vasculature, high nuclear EZH2 staining paralleled a significant reduction in VEC and Claudin-5, whereas PECAM1 expression was unaltered (lower, and 8C)." (PMID 29233846, 2018). "Both PECAM1 and ADCY7 promote tumor progression through the AKT pathway, showing the same molecular mechanism as CD300A." (PMID 29938007, 2018). "Consistent with the hemorrhagic tumor phenotype, active angiogenesis was found in these tumors, evidenced by immunostaining of platelet/endothelial cell adhesion molecule 1 (PECAM1)/CD31, an endothelial cell marker." (PMID 27344183, 2016). "Tumor cells of GL26-Cit tumor bearing mice fluoresced green and microvessels were labeled with blood vessel-specific anti-CD31 antibodies (i.e. anti-PECAM-1)." (PMID 27863376, 2016). "According to the changes observed in the vasculature, we completed the study with the expression analysis of endothelial-related genes in tumor lysates, such as CD31 (PECAM1), CD34, and VEGFR2 (KDR)." (PMID 27120788, 2016). "To validate our in vivo xenograft models used for experimental therapy, we have performed fluorescence immunohistology on explanted human tumor xenografts to detect NG2 and endothelial cell vessel marker CD31 (PECAM-1)." (PMID 26735180, 2016). "In contrast, PECAM1/CD31 and ANGPT1 were found downregulated in 80 % to 95 % of tumour samples with an average expression factor of 0.64 and 0.4, respectively." (PMID 26044849, 2015).
tumor (continued). "We have identified candidate gene expression (TGFa, PECAM1, and NRG1) in tumor for the prediction of sorafenib response and PFS by RNA sequencing." (PMID 26046304, 2015). "We assessed angiogenesis in these tumor tissues by staining for CD31 expression (also known as platelet/endothelial cell adhesion molecule 1, PECAM1)." (PMID 27462425, 2015). "A distinctive expression profile of VEGFA, EFNB2, PECAM1/CD31, ANGPT1 and ANGPT2 was revealed: VEGFA, EFNB2, and ANGPT2 were found overexpressed in 84 % to 95 % of tumour samples." (PMID 26044849, 2015). "We showed human PECAM1/CD31 and ENG/CD105 expression in all tumor types, supporting existence of human tumor endothelial cells in all tumor types." (PMID 24625025, 2014). "Due to the abnormal tumor vasculature, we also immunostained paraffin-embedded tumors from each mouse for host endothelial cell marker CD31/PECAM-1." (PMID 26932374, 2014). "The combination of various cytokines, including PECAM-1, VEGF, transforming GF and fibroblast GF, contributing to tumor angiogenesis would be a possible candidate for future study." (PMID 24959215, 2014). "Confocal imaging for endothelial marker PECAM-1 and αSMA revealed that, while NGP-LacZ control tumor EC had neighboring pericytes (arrows), NGP-N1D tumors developed segments of ECs that lacked pericyte coverage (arrowheads)." (PMID 24066611, 2013). "Regarding plasticity aspects, tumor tissue was stained for human, besides mouse, endothelial specific marker PECAM-1/CD31 (hPECAM-1 and mPECAM-1)." (PMID 23547746, 2013). "The VEGF secreted by the tumour cells and stroma then stimulates the expression and modulates the function of IgSF members such as ICAM-1, VCAM-1, and PECAM-1 in endothelial cells." (PMID 22272201, 2012). "The most commonly used antibodies to highlight tumor blood vessels are those against Factor VIII related antigen, CD31/PECAM-1, and CD34." (PMID 22481986, 2009). "In fact co-staining of tumor sections with PGP 9.5 and PECAM-1 showed colocalisation of these markers in the same vessels." (PMID 19551151, 2009). "The cell type-specific markers we used for cell annotation were as follows: T cell (CD3D); NK cell (KLRD1 and NKG7); plasma cell (IGKC and JCHAIN); Mast cell (KIT and TPSB2); tumour cell (CA9, NDUFA4L2 and SLC17A3); endothelium (PECAM1, PTPRB and KDR); mesangial cell (ACTA2 and PDGFRB)." (PMID 40830065, 2025). "Using the HPA, AGER, MGP, PECAM1, and SLC2A1, normal lung and LUAD tumor IHC staining was accessed." (PMID 40563443, 2025). "However, our NanoString data also showed downregulation of endothelial markers such as PECAM1 and VWF, alongside upregulation of the tumor microenvironment and fibrosis-related pathways in HCAECs." (PMID 41296447, 2025). "IHC analysis also revealed that PECAM1 had no staining in the LUAD tumor and had high staining in the normal lung, validating the downregulation of the gene in LUAD." (PMID 40563443, 2025). "We confirmed these findings in the snRNA-Seq dataset, where, as expected, PECAM1 expression levels were the highest in the endothelial cell population, followed by macrophages, whereas VEGFA expression levels were highest in the macrophages and tumour cells." (PMID 41168392, 2025). "EGFR and IDH1 were highly expressed in tumor cells, FAP and COL1A1 were confined to fibroblasts, CD68 and ITGAM marked macrophages, PECAM1 and CDH5 identified endothelial cells, OLIG2 and MOG were specific to oligodendrocytes, while CD4 and CD3D defined T-cell subsets." (PMID 41208987, 2025). "In addition, among many molecules involved in tumor angiogenesis, platelet-endothelial cellular adhesion molecule (PECAM-1), also known as CD31, has been widely used as a biomarker in highlighting tumor vascular invasion." (PMID 39012151, 2024). "CD31, also known as PECAM-1, is a widely used marker for assessing MVD in tumor tissues." (PMID 38748269, 2024).
tumor (continued). "Therefore, we further segregated ECs into tumor ECs (TECs) and normal ECs (NECs) using the TEC marker genes ENG, INSR, PECAM1, and SPRY1." (PMID 38182557, 2024). "Most of these cells were tumor epithelial cells, characterized by high expression of keratin 19 (KRT19) and low expression of PTPRC (CD45), PECAM1 (CD31), and PDGFRB, which are markers for immune/hematopoietic cells, endothelial cells, and stromal cells, respectively." (PMID 37966117, 2023). "It has been reported that the expression of PECAM1 in tumor tissue is highly correlated with the staging of non-small-cell LC." (PMID 36199786, 2022). "Changes in tumor EC properties under inflammatory conditions with direct consequences for leukocyte tumor infiltration are altered expression of P- and E-selectin, ICAM-1 and ICAM-2, VCAM-1 and CD31/PECAM-1." (PMID 35216427, 2022). "In addition, we found that TYMP significantly correlated with PECAM1, an indicator of microvascular density that was up-regulated in the PME, and positively correlated with tumor size and prognosis." (PMID 35314790, 2022). "It was shown in vivo that CTGF-knockout in mouse fibroblasts resulted in reduced neovascularization induced by the tumor, which was additionally confirmed by a decreased level of endothelial marker CD31/platelet endothelial cell adhesion molecule (PECAM-1) within the tumor and its stroma." (PMID 33430277, 2021). "The ECs-related genes such as ANGPT2, CD34, LYVE1, VWF and PECAM1 were highly upregulated in the vascularized tumor tissue as compared to non-vascularized tissue due to the presence of BVs." (PMID 34754042, 2021). "The results indicated that the expression of tumor cell-derived VEGFA, IGFBP3, EFNA1, EFNB1, IGF2, PDGFA and stroma-derived Angpt2, Cdh5, Esam, Esm1, Icam2, and Tie1 was statistically correlated with that of Pecam1 and elevated in p-EMT TW2.6 tumors." (PMID 34869001, 2021). "Therefore, the number of microvessels by staining CD31 (also called PECAM-1), a sensitive vascular marker, were analyzed to evaluate tumor angiogenesis in tumors." (PMID 33225938, 2020). "Furthermore, we concluded that if WNT2 is critically involved in tumor angiogenesis in humans, the outcome for overall survival would be influenced by WNT2 levels similarly to PECAM1 levels, directly indicating the amount of vascularization in the tumors." (PMID 31667643, 2020). "PECAM-1 and VEGF levels inbreast tumor cells were reduced by TVSE administration." (PMID 33152052, 2020). "To assess whether expression of tdTomato correlated with the extent of hypoxia and vascularisation, we stained frozen tumour sections for EF5 (an exogenous hypoxia marker) and CD31 (PECAM1)." (PMID 32571767, 2020). "CD31, also known as platelet endothelial cell adhesion molecule-1 (PECAM-1), is a membrane glycoprotein highly expressed in early and mature endothelial cells, and commonly used as a staining marker for microvessels in evaluation of tumor angiogenesis." (PMID 31996731, 2020). "In conclusion, we observed increasing recruitment of VEGFR1+CD133+ HPCs to the lung during tumor metastasis and found high expression of CXCL-16, IL-2Rα, IL-2Rγ, MMP-1, MMP-9, PDGFR-α, SDF-1α, TGF-β, PECAM-1, and VE-cadherin in highly metastatic MDA-MB-435s cells." (PMID 30483898, 2019). "As expected, the increased protein expression of HIF-1α, VEGF, pVEGFR2, and CD31 (PECAM-1), a specific endothelial cell marker, in tumor tissues determined by immunohistochemical staining or Western blotting assay was also greatly suppressed after AE-AS treatment." (PMID 28710377, 2017). "Platelet endothelial cell adhesion molecule (PECAM-1) staining showed that none of the endothelial cells within the tumour stained positively for E2C, indicating that they were all derived from the host." (PMID 29271879, 2017).
tumor (continued). "To obtain further insight into tumor vascularization and VEGFR expression by cancer and non-tumor cells, we used real-time qRT-PCR to quantify species-specific mRNAs of PECAM1/CD31, ENG/CD105, FLT1/VEGFR1, KDR/VEGFR2 and VEGFA genes in a large series of 150 xenografts from different tumor types." (PMID 24625025, 2014). "First, studies using CD31 knockout mice demonstrate the requirement of PECAM-1 in modulating T-cell responses, because mice lacking CD31 exhibited enhanced tumor and allograft rejection compared to wild-type mice." (PMID 25705515, 2014). "To further identify whether the downregulation of MMP-2 in endothelial cells is associated with MT1-MMP, which facilitates peri/extracellular pro-MMP-2 activation, we performed triple-fluorescence immunostaining for PECAM-1, MMP-2 and MT1-MMP on tumor tissue." (PMID 22545131, 2012). "As lower expression of Lyve1 in tumor sites was identified by spatial transcriptomics analysis in this study and lymphatic angiogenesis was often driven by VEGF-families, we subsequently explored the correlation of VEGF-families with CCL21, CCL19, Pecam1 (CD31) and Lyve1 by the TCGA database of HCC." (PMID 40685403, 2025). "Second, tumor subsets enriched for microenvironment features, including hypoxia markers (e.g., Slc2a1, Pdk1, Car9), extracellular matrix (ECM) genes (e.g., Matn2, Fn1, Dcn, Col6a1), vasculature (e.g., Cdh5, Pecam1, Vwf), and interferon response genes (e.g., Rsad2, Ifit3, Gbp3, Cxcl10, Cd274)." (PMID 40171265, 2025). "Using scRNA-seq on tumor tissues from 12 treatment-naïve GBC patients (GBC1–12) and benign gallbladder tissues from six chronic cholecystitis patients (CC1–6), the authors isolated 8897 endothelial cells (endothelial markers: CD34, PECAM1, VWF) and subclustered them into eight endothelial subtypes." (PMID 41154806, 2025). "Studies were completed by immunohistochemistry with the endothelial cell marker CD31 (also known as PECAM-1 or Platelet Endothelial Cell Adhesion Molecule-1), a transmembrane glycoprotein expressed by endothelial cells to assess the evolution of vascular density and vascular integrity in the tumor." (PMID 39143719, 2024). "As a quality check of the enriched population, we assessed that the isolated cells lacked expression of tumor (dsRED), immune (Ptprc) and endothelial markers (Pecam1) and expressed the mouse CAF-specific signature we previously identified (e.g. Rarres2, Fap, Lum, Thy1)." (PMID 38509063, 2024). "We also confirmed that 4 genes (PECAM1, TIMP1, CXCL5 and PDGFB) were correlated with the expression of the VEGF family, suggesting that these genes may work together with the VEGF family to promote tumor LYM." (PMID 38638428, 2024). "Moreover, PECAM1+ cells (ECs) in cluster 8 ECS (COL1A1, COL1A2, COL3A1, PDGFRB, and ACTA2) showed an endothelial-mesenchymal transformation phenotype, which contributed to tumor progression." (PMID 37533434, 2023). "Yet, NKX2–1 tumours do not show altered endothelial CD31/PECAM-1 staining patterns." (PMID 36932191, 2023). "Furthermore, the blood vessel density stained by PECAM1 (CD31) showed a trend of elevation in the PAK4 knockdown (KD) tumour, despite not reaching statistical significance." (PMID 38067120, 2023). "PECAM-1 has been found to positively correlate with MELD, and its identification may aid in assessing the degree of tumor angiogenesis, which may indicate a rapidly growing tumor." (PMID 36675666, 2022). "A total of 225 high-quality cells from control and 356 from tumor-draining LNs were included in the downstream analysis and their LEC identity could be confirmed by the expressions of endothelial cell markers Cd31 (Pecam1) and VE-cadherin (Cdh5) as well as lymphatic markers Prox1 and Vegfr3 (Flt4)." (PMID 35892863, 2022).
tumor (continued). "However, in our study, when we measured the markers of TAMs, including HIF-1α, CCL2, and PECAM1, we found that gemcitabine treatment potently activated the expression of TAM markers, while knockdown of IFI16 reversed the increase in TAMs in the tumor microenvironment." (PMID 34150748, 2021). "Hence, tumour-specific FCER1G and PECAM1 may represent bona fide therapeutic targets that warrant further evaluation." (PMID 29784888, 2018). "PECAM-1 has been described as engaging in both homophilic and heterophilic adhesive interactions, and it is possible that the interaction of PECAM-1 with heparan sulfate proteoglycans on tumour cells could contribute to extravasation." (PMID 22272201, 2012). "To explore this hypothesis, we investigated the relationship between tumor-stroma interaction as quantified by our model and the expression of the stromal markers ACTA2 — using α-smooth muscle actin (αSMA), a marker for activated fibroblast — and PECAM1 — using CD31, a marker for angiogenesis." (PMID 36647832, 2023). "The IHC showed that AGER and PECAM1 have high intensity and strong staining in all normal lung samples (3/3 subjects), whereas in LUAD tumor tissues, these proteins were absent (0/5–6 showed any positive staining)." (PMID 40563443, 2025). "Co-staining with the endothelial cell marker PECAM-1 revealed endothelial-specific staining for JAM-C on LLC tumor vessels, while tumor cells were negative for JAM-C." (PMID 32054130, 2020). "In HSA/TIMP-2-treated tumor tissues, MMP-2 expression was profoundly decreased without a change in MT1-MMP expression of PECAM-1-positive cells." (PMID 22545131, 2012). "Interestingly, the PECAM1/SPP1 correlation analysis indicates that healthy lung tissues are mostly PECAM1highSPP1,low while tumor samples appear PECAM1lowSPP1high (data not shown)." (PMID 40028673, 2025). "To investigate the molecular determinants of the different angiogenic patterns, we studied the expression of various genes involved in the control of tumor angiogenesis but no relevant variations (data not shown) were observed for several of these (FGF2, PECAM1, MCAM, COX2)." (PMID 28903354, 2017). "Although the expression of six endothelial differentiation marker genes (PECAM1, vWF, FLT1, FLT4, KDR, CDH5) was significantly lower in normal and tumor ADSC, there was significantly greater expression of PDGFRB in ADSC when compared to BEC and NORMA1 MEC cells." (PMID 26968831, 2016). "Interestingly although this elevated expression was indicated from transcript analysis using CLEC14A/PECAM1 ratios, it was not from CLEC14A/TIE1 ratios, implying that in this tumour elevated CLEC14A expression may be more a result of reduced flow rates." (PMID 32696621, 2020). "However, it is interesting to note that CD300A inhibits the apoptosis through PECAM1 but not ADCY7 in U937 cells, implying the unknown mechanisms by which CD300A promotes tumor progression." (PMID 29938007, 2018). "Quantitative analysis indicated that the level of MT1-MMP in PECAM-1-positive blood vessels did not significantly differ between control and HSA/TIMP-2-treated tumors (P = 0.918), which was confirmed by western blotting of tumor lysates from the HSA/TIMP-2-treated group (P = 0.096)." (PMID 22545131, 2012).